BRAF (B-Raf proto-oncogene, serine/threonine kinase)
Diseases named in the same sentence as BRAF in open-access papers (continued):
Sharing a sentence is not in itself a finding about the gene and the disease.
melanoma (continued). "The synergistic impact on cell viability with the addition of a SRC inhibitor to BRAF + EGFR targeting was conserved across BRAFV600E CRC cell lines, but not BRAFV600E melanoma cells." (PMID 36759733, 2023). "Unlike BRAF-mutant melanoma cells, STAG2 knockdown in BRAF-mutant thyroid cancer cells did not affect their cellular response to MEK inhibitor." (PMID 37479689, 2023). "RepID is a crucial player for cell proliferation in driver-negative tumors, including melanoma, breast, and lung cancers which lose HER2, EGFR, ALK, or BRAF expression." (PMID 37461562, 2023). "Scientific evidence has confirmed that targeting intracellular signaling pathways such as RAS/BRAF/MAPK and PI3K/AKT in the treatment of malignant melanoma has not been adequate." (PMID 35656077, 2022). "Although MEK2 and BRAF kinase are part of the same MAPK signaling pathway, MEK2, however, has not yet been shown to possess any effect on the melanoma pathogenesis." (PMID 36014478, 2022). "RIPK1 is described as an oncogenic driver in melanoma due to its scaffold function independent of the kinase function, while RIPK3 expression apparently is suppressed by the BRAF and AXL oncogenes." (PMID 35422482, 2022). "In melanoma experiences, while administering an anti-MEK agent after BRAF inhibition failure is not very effective, the administration of both drugs simultaneously improves objective responses and survival and actually represents a standard of care." (PMID 36686797, 2022). "This is highly relevant because, as opposed to previous studies, STARBOARD is using front-line anti-PD-1 immunotherapy for comparison, as opposed to BRAF/MEK inhibitors, which currently are rarely used as first-line therapy for melanoma treatment." (PMID 36232957, 2022). "Immunoblotting with phospho-specific antibodies confirmed these results in all BRAFV600E melanoma cells treated with either PLX4032 or GSK2118436 and lack of effect in WT BRAF MeWo cells." (PMID 35944584, 2022). "However, cobimetinib plus atezolizumab did not demonstrate a longer PFS than pembrolizumab alone in BRAF wild-type melanoma (5.5 vs. 5.7 months, respectively; p = 0.30), which showed that the combination of a MEK inhibitor and ICIs might not be more effective in these patients." (PMID 36145516, 2022). "There have been no prospective trials to date regarding the efficacy of BRAF and MEK inhibition for melanoma LM." (PMID 35790709, 2022). "RAC1/P29S expression alone in mouse melanocytes did not result in melanoma; however, in combination with mutant BRAF, RAC1/P29S expression resulted in melanoma in these mice." (PMID 35454871, 2022). "We did not identify BRAF or NRAS alterations, which are typical for the most common melanoma pathway–MAPK cascade." (PMID 35621644, 2022). "Furthermore, we confirmed elevated expression of human DGAT1 but not DGAT2 mRNA in melanoma tumors relative to both skin and nevi and elevated DGAT1 protein in human melanoma cell lines relative to primary melanocytes irrespective of NRAS or BRAF mutational status." (PMID 35732120, 2022). "Strong initiators of melanoma, like NRAS61R and NRAS61K, showed higher BRAF affinity (lower BRET50) than weaker and non-melanogenic alleles like NRAS61H, NRAS61P, and NRAS12D." (PMID 35672316, 2022). "In this review, we present the current knowledge on the immunomodulatory functions of BRAF/MEKi as well as the non-intended effects of ICI and discuss the potential synergistic effects of ICI and MAPK inhibitors in melanoma treatment." (PMID 34576054, 2021). "In addition, in the last case, not only is the BRAF status not always representative of the current status, but when the primitive tumor is a thin melanoma, the number of neoplastic cells may not be enough for the assessment of BRAF mutation with classical extractive methods." (PMID 34207125, 2021). "TCGA analysis detected fusions in BRAF and RAF1 kinases in melanomas, but did not report fusions in ALK, ROS1, MET, RET, or NTRK, which are clinically targetable." (PMID 34831002, 2021).
melanoma (continued). "Co-culture of melanoma cells with TAB cells, but not normal B cells, led to the development of resistance to BRAF and MEK inhibitors as well as cisplatin and paclitaxel treatment." (PMID 34830951, 2021). "In this study, we demonstrate that although CDK4/6 inhibition does not potentiate the metabolic effects of BRAF and MEK inhibition in melanoma, there is a significant upregulation of mitochondrial activity following CDK4/6 inhibition." (PMID 33572972, 2021). "In NRAS mutant melanomas, the inhibition of PKA signaling (that prevents CRAF inactivation) leads to the negative feedback inhibition of BRAF and promotes CRAF-mediated MAPK signaling instead." (PMID 34831002, 2021). "Cutaneous melanoma can be divided into chronically sun-induced melanoma (CSID), non-chronically sun-induced melanoma (non-CSID) and the four genomic subtypes, BRAF, RAS, NF1, and triple wild-type." (PMID 34359771, 2021). "Considering the lack of success of therapies targeting BRAF and MEK in NRAS mutant melanoma patients, recent efforts have been focused on finding other therapeutic targets and the development of combination therapies." (PMID 33921974, 2021). "Classical morphological, immunohistochemical and the well-known BRAF and NRAS genetic biomarkers do not allow the correct categorization of patients, being melanoma conditioned by high genetic heterogeneity." (PMID 34207514, 2021). "Unfortunately, as with BRAF and MEK inhibitors, people with melanoma sometimes do not respond to therapy or become resistant to this form of treatment." (PMID 34681580, 2021). "At the moment, there are no approved targeted therapies for advanced melanoma patients harboring class II and class III non-V600 BRAF mutants." (PMID 33917428, 2021). "The use of MAPK inhibitors to radio-sensitize tumors to TRT appears to be a promising strategy in BRAF- and NRAS-mutant melanoma, although the lack of an in vivo study to confirm the results is the main limitation of this work." (PMID 33804655, 2021). "Several studies have tested this anti-BRAF therapy in the setting of CRC, but in contrast to the results observed in BRAF V600E melanoma, vemurafenib as a single therapy did not demonstrate any clinically relevant activity in BRAF mutant metastatic CRC." (PMID 34063682, 2021). "We show that the novel non-nucleoside RTI, SPV122 synergizes with BRAF and MEK inhibitors to: 1) impair BRAF-mutant melanoma cell growth; 2) induce apoptosis; 3) block cell cycle progression and 4) delay the emergence of resistance in vitro." (PMID 33757523, 2021). "Clinical outcomes following treatment with one class of drugs (such as BRAF or MEK/ERK inhibitors) for TC and melanoma are not impressive." (PMID 33578751, 2021). "Usp9x KD but not Usp34 KD reduced SOX2 levels in both BRAF mutant A375, SK-Mel28, and NRAS-mutant SK-Mel147 melanoma cell lines." (PMID 33613844, 2021). "In melanoma, dual rather than single inhibition of the MAPK pathway (BRAF and MEK co‐inhibition) has been shown to significantly prolong the duration of response to therapy." (PMID 35847743, 2020). "Unfortunately, as in the case of BRAF and MEK inhibitors, melanoma patients sometimes do not respond or become resistant to this form of treatment." (PMID 33171792, 2020). "Cases of melanoma were described in the NRAS‐mutant and one in the double wild‐type group, and although no cases were described in BRAF‐mutant patients this is statistically compatible with the rarity of this genotype." (PMID 31111470, 2020). "PHI1 also exhibited a co-operative mode of inhibition in oncogenic non-V600E BRAF dimers belonging to class-II and class-III, but not in RASMUTBRAFWT driven melanomas." (PMID 32873792, 2020). "Patient No 9, with irresectable tumor stage IIID melanoma, received T-VEC following a targeted therapy with BRAF/MEK inhibition." (PMID 32052079, 2020).
melanoma (continued). "While treatment with BRAF- and MEK-inhibitors is not sufficient to overcome HGF-induced resistance, BRAF- and MET (the HGF receptor)-inhibitors suppress the majority of HGF-induced drug resistance in BRAF-mutant melanoma." (PMID 31067787, 2019). "In contrast, the combination of PLX4720 and α-amanitin did not increase the apoptotic rate in the BRAF- and NRAS-wildtype melanoma cell line MeWo." (PMID 31123282, 2019). "Similar results were obtained in other BRAFV600E-positive melanoma cells such as G361 and SK-MEL-5, but not in MeWo and NRAS mutant SK-MEL-2 cells that contain WT BRAF." (PMID 30979895, 2019). "Here, the authors show that in response to pro-inflammatory cytokines, ITCH mediates a non-proteolytic ubiquitination and activation of BRAF, which in turn sustains MEK/ERK signaling to facilitate melanoma cell growth." (PMID 31015455, 2019). "To do this, we analyzed BRAF, NRAS and TERT promoter mutant ctDNA using serial blood samples from melanoma patients with and without confirmed disease recurrence." (PMID 30719207, 2019). "Although its role during development is not yet clear, its expression in melanocytes prevents BRAF-induced senescence and leads to proliferation, suggesting a role for BRN3A in melanoma transformation." (PMID 31118886, 2019). "Since there are hardly any publications on BRAF and NRAS wild type melanoma brain metastases cell lines, there are no results regarding the xenotransplantation behavior of this type of cells." (PMID 30858407, 2019). "Taken together, oncogenic BRAF targeting inhibits the processing and activation of SREBP-1 in therapy-sensitive, but not therapy-resistant, melanoma cells and this effect is, by and large, mediated by a post-translational mechanism." (PMID 29950559, 2018). "We now show, that PI3K/AKT signalling via potent oncogenic PIK3CA and AKT3 mutants, is not sufficient to overcome proliferative arrest induced by BRAF/MEK inhibition, but rather enables the survival of a dormant population of MAPK-inhibited melanoma cells." (PMID 30237495, 2018). "A small proportion of resistant melanomas rely on the activation of the compensatory PI3K/AKT signalling cascade, although activation of this pathway does not preclude patient responses to BRAF/MEK inhibition." (PMID 30237495, 2018). "In both the 1205Lu BRAF‐mutant melanoma cell line and the WM1366 NRAS‐mutant melanoma cell line, treatment with dabrafenib, but not vemurafenib, led to abrogation of RB protein phosphorylation and strong upregulation of p27." (PMID 29112787, 2018). "Targeted cancer therapies have shown some progress in treating BRAF‐mutant melanoma, but not against NRAS‐mutant and treatment‐resistant melanoma." (PMID 29661909, 2018). "Evaluation of clinical data also suggests that PI3K/AKT activation is not sufficient to confer BRAF and MEK inhibitor resistance in melanoma." (PMID 30237495, 2018). "Paradoxically, CRAF but not BRAF was shown to be critical for various RAS-driven cancers, raising the question of the role of RAF proteins in NRAS-induced melanoma." (PMID 28497782, 2017). "In the context of FDA approved therapies targeting melanoma biomarkers such as BRAF, MEK and VEGF, it is safe to say that biomarkers can not only serve as prognostic tools but are also useful in developing new therapies targeting melanoma." (PMID 28567163, 2017). "ERBB3 triggers survival cues to melanoma cells regardless of their oncogenic drivers; ERBB3 is also a mechanism of resistance to BRAF inhibitors; and promotes melanoma metastasis." (PMID 28060735, 2017). "It has been demonstrated that serum level of HGF significantly correlates with the stage of melanoma, although patient evaluation did not provide unambiguous results to validate HGF as a biomarker for melanoma response to BRAF inhibitors." (PMID 28829835, 2017).
melanoma (continued). "Because the early development of the lineage is not altered in BRAF and CRAF KOs, these models allowed us to investigate the role of both RAF kinases in tumour progression from initiation to malignant melanoma." (PMID 28497782, 2017). "Usp9x KD reduced the stability of Ets-1 in both BRAF and NRAS mutant melanoma and decreased NRAS, but not total RAS protein levels." (PMID 28198367, 2017). "Amplification of NRAS was detected in 6.3% (2/32) and 9.5% (2/21) of BRAF/NRAS WT and High non-HET melanomas, respectively." (PMID 28668077, 2017). "Disomy of NRAS/chromosome 1 (with or without polysomy in few cells) were detected in 59.4% (19/32) of BRAF/NRAS WT, 50% (15/30) of HET, but in only 28.6% (6/21) of High non-HET melanomas (P = 0.08)." (PMID 28668077, 2017). "Thus, disruption of ROS regulation in melanoma cells, in which the levels of ROS might be quite high already, might explain why they respond more strongly by undergoing cell death than their isogenic counterparts in which the BRAF pathway is not overactive." (PMID 26029997, 2015). "Analysis of 16 pan-negative melanoma cell lines revealed that 8 (50%; termed Class I) are sensitive to the MEK1/2 inhibitor, trametinib, similar to BRAF V600E melanomas." (PMID 26084293, 2015). "Immunohistochemical analysis of BRAF-mutant, NRAS-mutant and pan-negative patient melanomas revealed wide heterogeneity of DUSP4 expression in each subtype." (PMID 26084293, 2015). "While BRAF inhibitors are initially effective for BRAF-mutant melanoma, no FDA-approved targeted therapies exist for BRAF-inhibitor-resistant BRAFV600, NRAS mutant, or wild-type melanoma." (PMID 25142146, 2014). "BRAF and NRAS status also had no impact on the disease-free interval from the diagnosis of the primary melanoma to nodal metastases." (PMID 24959217, 2014). "Similar to what was seen for BRAF, NRAS expression levels were found to be significantly higher in malignant melanomas than in non-malignant nevi (p = 0.018)." (PMID 23673558, 2013). "Since the development of more potent BRAF inhibitors, clinical evaluation of RAF-265 inhibitor as a single-agent treatment for melanoma patients is not a strong focus." (PMID 23515890, 2013). "Emerging approaches such as BRAF inhibition (PLX4032,) and immune-based therapies hold great promise, but are unlikely to be effective for all melanoma patients." (PMID 22536322, 2012). "As such, sequential targeting of the MAPK pathway at multiple nodes in BRAF mutant patients (irrespective of their RAS mutational status) or targeting of parallel pathways, such as PI3K, in RAS mutant patients, may also improve the therapeutic response of melanoma patients to MEK1/2 inhibition." (PMID 23039341, 2012). "Knock-down of BRAFV600E in these melanoma cells elevates basal pAKT and downstream signals, whereas knock-down of CRAF, MEK1/2 or ERK1/2 or treatment with a BRAF inhibitor have no impact on pAKT." (PMID 22880048, 2012). "Drugs targeting BRAF, MEK, and Hsp90 (but not ERK) are in development, and clinical trials are ongoing to evaluate their efficacy in melanoma." (PMID 21479172, 2011). "As in melanoma cells, BRAF and MITF are both essential for melanocyte proliferation, but in contrast to melanoma cells, MITF expression does not depend on BRAF expression or MEK/ERK signalling in melanocytes." (PMID 18628967, 2008). "In melanomas that arise outside of an epithelium, such as in the dermis and eye, MAPK pathway activation is most frequently achieved through the activation of Gαq/11 signaling, rather than directly through BRAF or NRAS." (PMID 39804140, 2025). "Based on the observation that the CDK4/6 pathway is frequently altered in melanoma, CDK4/6 inhibitors have emerged as potential agents for treating patients with NRAS-mutant and BRAF-wild-type tumors that have not lost the tumor suppressor retinoblastoma protein (pRb)." (PMID 40904502, 2025).
melanoma (continued). "To determine whether NR2F1 is sufficient to enhance drug tolerance, we induced the expression of NR2F1 in BRAF-V600E 1205Lu, WM793, and A375 melanoma cell lines and treated them with or without BRAFi + MEKi." (PMID 40955663, 2025). "The interplay between targeted drugs and TIL-Bs may vary; in melanoma, a negative correlation was observed between TIL-Bs and the efficacy of BRAF and MEK inhibitors." (PMID 41285707, 2025). "Unlike ICB, the objective response rates (ORR) obtained with BRAF/MEKi, in BRAFV600-mutant AJCC stage IV-M1d melanoma are similar to patients without MBM, irrespective of whether the MBM are symptomatic." (PMID 39682270, 2024). "After treatment with BRAF/MEK inhibitors, melanoma cells lacking GSDME exhibited impaired infiltration of tumor-associated T cells, the number of activated dendritic cells was diminished, and a higher incidence of tumor regrowth after cessation of drug treatment was recorded." (PMID 38336727, 2024). "The majority of melanoma LMD patients do not respond to MAPK-targeting therapy, and we recently showed that CSF from these patients could modulate BRAF inhibitor responses and contribute to drug resistance." (PMID 38866016, 2024). "Furthermore, the downregulation and overexpression of RIPK4 did not alter the activity of the BRAF, MEK, or ERK1/2 proteins in any of the melanoma cell lines." (PMID 36765875, 2023). "However, melanoma cells express little EGFR; therefore, BRAF inhibitors did not stimulate EGFR activation." (PMID 37218919, 2023). "However, a phase II study investigating the combination in BRAF/NRAS wild-type, and NRAS-mutant melanoma patients (NCT01941927) revealed no improvement to overall or progression-free survival." (PMID 37181747, 2023). "Furthermore, AR was found significantly associated with OS in RAS mutant subtypes of melanoma but not in BRAF, NF1, or triple-wild type subtypes of melanoma." (PMID 36833272, 2023). "The CheckMate‐037 trial, which evaluated nivolumab versus chemotherapy in patients with advanced melanoma who progressed after anti‐CTLA‐4 treatment, noted statistically better ORR in BRAF‐wildtype group with nivolumab, but no statistical difference in the BRAFV600 mutant patients." (PMID 37403699, 2023). "In fact, melanoma cell lines treated for only 24 h or from 48 to 72 h with BRAFi, MEKi, or ERKi, display spindle-shaped and/or flat morphology, regardless of the MAPK oncogenic driver (BRAF or NRAS mutant)." (PMID 35159327, 2022). "Both target therapy with BRAF inhibitors + MEK inhibitors and immunotherapy with anti-checkpoint blockades are effective in melanoma V600K, although no sufficient evidence can currently support a formal recommendation for first line treatment choice in IIIC unresectable/IV stage patients." (PMID 35160279, 2022). "Due to the success of BRAF inhibitors in other tumors, several studies have evaluated the use of BRAF inhibitors with or without MEK inhibitors in metastatic CRC (mCRC) but without achieving the same benefits as in melanoma." (PMID 36589179, 2022). "However, a recent study showed that in mice bearing BRAF V600E mutant and NRAS Q61R mutant xenografts, KBs had no direct effect on melanoma cell growth, whereas a KD slowed tumor." (PMID 36432618, 2022). "In addition, therapeutic options for some non-eligible melanoma patients (for example, RAS mutant or triple BRAF/NRAS/NF1 wild-type melanoma patients) are more limited." (PMID 35159327, 2022). "Use of BRAF inhibitors was shown to enhance the immunogenicity of Melanoma without negatively effecting T-cell function possibly through increases in HLA expression, however, other studies observed reduced TIL in BRAF treated tumour models." (PMID 34960140, 2021).